RNU1-151P (RNA, U1 small nuclear 151, pseudogene)
Gene: Small nuclear RNA gene on chromosome 1 (147,079,746 to 147,079,870, forward strand). Ensembl gene ENSG00000201142.
Homologues: Orthologues: chimpanzee U1 (99% identical), dog U1 (74% identical), rabbit U1 (70% identical), dog U1 (69% identical), guinea pig U1 (69% identical), dog U1 (67% identical), dog U1 (66% identical), dog U1 (65% identical), rabbit U1 (62% identical), dog U1 (61% identical), rabbit U1 (61% identical), rabbit U1 (60% identical), and 1 more. Paralogues in human: RNU1-114P (90% identical), RNU1-129P (87% identical), RNU1-154P (86% identical), RNVU1-31 (74% identical), RNU1-1 (74% identical), RNU1-2 (74% identical), RNU1-27P (74% identical), RNU1-28P (74% identical), RNU1-3 (74% identical), RNU1-4 (74% identical), RNVU1-18 (74% identical), RNVU1-29 (74% identical), and 134 more.